LMO4 (LIM domain only 4)
Diseases named in the same sentence as LMO4 in open-access papers (continued):
Sharing a sentence is not in itself a finding about the gene and the disease.
cancer (19 papers, 2003 to 2025). A tumor composed of atypical neoplastic, often pleomorphic cells that invade other tissues. "Certain lncRNAs have been reported to facilitate cancer progression by positively regulating LIM-only protein 4 (LMO4)." (PMID 34447693, 2021). "Thus, dysregulation of LMO4 plays an important role in the carcinogenesis of cancer." (PMID 34925640, 2021). "We also compared the resistant subclone C3 to C2 and C4, identifying LMO4 upregulated in C3, a marker of cell proliferation and invasion, and EFNA5 up-regulated in C2 and C4, a gene regulating cancer cells invasion." (PMID 37917660, 2023). "LMO4 mRNA was amplified in four of six carcinoma tissues and eight of 12 carcinoma cell lines, and LDB1 in three carcinoma tissues and 11 cell lines examined." (PMID 12771919, 2003). "Finally, we demonstrate the involvement of LMO4 and LDB1 in cancer cell proliferation, invasiveness, migration, and angiogenesis, suggesting these nuclear proteins are important regulators of growth and metastasis in HNSCC." (PMID 27780223, 2016).
tumor (12 papers, 2008 to 2024). "To evaluate whether loss of Lmo4 could affect tumour initiation, we collected mice of each genotype 12 weeks after Ad5-CMV-cre administration." (PMID 26048572, 2015). "Given that Lmo4 is involved in the regulation of the proliferation of epithelial cells after naphthalene injury, we assessed whether loss of Lmo4 would affect initiation of tumor growth in naphthalene-mediated sensitization of K-RasG12D-driven tumors." (PMID 26048572, 2015). "The expression of FOXM1 was increased while that of Linc-ROR, LMO4, and Ki-67 was decreased in the tumor tissue of the mice in the oe-FOXM1 + sh-Linc-ROR group when compared with the oe-FOXM1 group." (PMID 34447693, 2021). "Overexpression of LMO4 promotes cell proliferation, invasion, and tumor formation and induces mammary hyperplasia in transgenic mice." (PMID 31910858, 2020). "Taken together, these results revealed the tumor-suppressor role of the miR-139-5p/LMO4 pathway in PTC." (PMID 30796202, 2019). "The miR-18b-5p is a known tumor suppressor, while LMO4 a known oncogene." (PMID 35629174, 2022). "Furthermore, the elevated expression of ASCL1 and LMO4 seen in the MYCN-overexpressing SY5Y-MYCN cells matched the high expression of these genes in the poor outcome tumours." (PMID 28187790, 2017). "As we did not observe any effect of Lmo4 loss on tumor-free survival in this model, we decided to further determine LMO4 expression in the different subtypes of NSCLC in early stage disease." (PMID 26048572, 2015). "Our results showed that in the context of naphthalene-induced sensitization of K-RasG12D-driven carcinogenesis, loss of Lmo4 reduced cell proliferation and delayed the onset of transformation but did not affect overall survival or tumor latency." (PMID 26048572, 2015). "Taken together, it remains unclear if LMO4 has an oncogenic function or a tumor suppressive function in pancreatic carcinogenesis." (PMID 19099607, 2008). "After that, the expression of LMO4 was analyzed; we found that LMO4 expression was upregulated in PTC tumor tissues at mRNA and protein levels." (PMID 34925640, 2021). "Conversely, tumours with low ASCL1 and LMO4 expression had better prognosis, matching the cell line results in which these genes were downregulated by RA." (PMID 28187790, 2017). "Additionally, Lmo4 was found to modulate the early proliferative response observed after activation of oncogenic K-RasG12D expression in the context of naphthalene sensitization, although loss of Lmo4 did not affect overall tumor-free survival." (PMID 26048572, 2015). "The RT-qPCR, Western blot and IHC results indicated that overexpression of FOXM1 upregulated the expression of Linc-ROR, LMO4, and Ki-67, while silencing of Linc-ROR downregulated the expression of LMO4 and Ki-67 as well as unchanged FOXM1 expression in the tumor tissues." (PMID 34447693, 2021). "We then assessed whether Lmo4 participated in tumor growth in the K-RasLSL-G12D model in the absence of naphthalene sensitization." (PMID 26048572, 2015). "Together these results show that the transcriptional regulator Lmo4 participates in the regulation of lung epithelial cell proliferation in the context of injury and oncogenic transformation but that Lmo4 depletion is not sufficient to prevent lung repair or tumour formation." (PMID 26048572, 2015).
infection (2 papers, 2024 to 2026). The state of being infected such as from the introduction of a foreign agent such as serum, vaccine, antigenic substance or organism. "Upon infection with H. polygyrus, the IL-33 alarmin accumulated in the bone marrow, causing EMPPs to upregulate the GATA co-factor LMO4 and preferentially differentiate into myeloid cells." (PMID 41813898, 2026). "Similar to primary infections, we also observed that overexpression of LMO4 boosted secondary memory CD8+ T-cell polyfunctionality." (PMID 39117617, 2024). "Thirty days after primary infection with gp100-vv, we isolated pmel-1 T cells overexpressing Lmo4-Thy1.1 or Thy1.1 and transferred them in equal numbers into new wild-type hosts together with a type 2 adenovirus encoding gp100 (gp100-Adv)." (PMID 39117617, 2024). "Having established LMO4 as a key regulator of CD8+ T-cell differentiation and formation of stem-like memory T cells, we next investigated if LMO4-overexpression could promote more robust recall responses after secondary infection." (PMID 39117617, 2024).
adenocarcinoma (1 paper, 2015). A common cancer characterized by the presence of malignant glandular cells. "Gene expression profiling analysis of lung tumors showed that LMO4 is highly expressed in advanced adenocarcinomas, which prompted us to analyse its role in K-RasG12D mouse model of adenocarcinoma." (PMID 26048572, 2015). "Using CMV-cre adenoviruses to activate K-RasG12D expression and deplete Lmo4 expression, we targeted all cell types in the lung, including alveolar type II cells that are the predominant cell of origin in K-RasG12D-induced adenocarcinoma but do not express Lmo4." (PMID 26048572, 2015).
hematologic malignancies (1 paper, 2024). "We demonstrated that LMO4 overexpression enhances antitumor T cell responses across various models, encompassing solid cancers and hematologic malignancies, in both syngeneic and xenograft settings." (PMID 39117617, 2024).
LMO4 also shares sentences with these, for which no sentence is quoted: adenosquamous carcinoma (1 paper); Alzheimer disease (1); Cognitive impairment (1); COVID-19 (1); familial breast cancer (1); glioblastoma (1); glioma (1); hearing loss (1); invasive breast carcinoma (1); leukemia (1); metastatic tumors (1); neurological disorders (1); pancreatic adenocarcinoma (1); papillary thyroid carcinoma (1); T-cell acute lymphoblastic leukemia (1); T-cell leukemia (1).